KDM3B (lysine demethylase 3B)
Description:
Histone demethylase that specifically demethylates 'Lys-9' of histone H3, thereby playing a central role in histone code. Demethylation of Lys residue generates formaldehyde and succinate. May have tumor suppressor activity.
Synonyms: C5orf7; JMJD1B; KIAA1082; NET22; 5qNCA; DIJOS
Tractability: Small molecule: a structure with a bound ligand is known. PROTAC: UniProt records ubiquitination sites on it; ubiquitination databases record sites on it; its protein half-life has been measured.
Target class: Epigenetic regulator; Jumonji domain-containing; Eraser; Lysine demethylase
Gene: Protein-coding gene on chromosome 5 (138,352,681 to 138,437,028, forward strand). Ensembl gene ENSG00000120733.
Subcellular location: Nucleus
Subcellular location (Human Protein Atlas): Nucleoplasm; Golgi apparatus
Pathways (Reactome):
Chromatin organization: HDMs demethylate histones
Gene Ontology:
Molecular function: transcription coregulator activity; histone H3K9 demethylase activity; histone H3K9me/H3K9me2 demethylase activity
Biological process: regulation of transcription by RNA polymerase II; chromatin remodeling
Cellular component: nucleoplasm; histone deacetylase complex; nucleus
Genetic constraint (gnomAD): Loss-of-function variants: 10 observed, 144.93 expected, observed/expected ratio (o/e) 0.069, 90% interval 0.042 to 0.12. The upper end of that interval is the gene's LOEUF score, 0.12, which puts it in group 1 of 6, group 1 being the genes least tolerant of losing a copy. Missense variants: 1,278 observed, 2,050.1 expected, observed/expected ratio (o/e) 0.62, 90% interval 0.59 to 0.65. Synonymous variants: 757 observed, 788.05 expected, observed/expected ratio (o/e) 0.96, 90% interval 0.9 to 1.02.
Gene-disease validity (ClinGen):
ClinGen rates the evidence that KDM3B causes each of these diseases.
syndromic intellectual disability (autosomal dominant): Definitive. A intellectual disability that is part of a larger syndrome.
Homologues: Orthologues: chimpanzee KDM3B (99% identical), macaque KDM3B (99% identical), rabbit KDM3B (97% identical), pig KDM3B (96% identical), dog KDM3B (94% identical), mouse Kdm3b (93% identical), rat Kdm3b (93% identical), guinea pig KDM3B (92% identical), tropical clawed frog kdm3b (67% identical), zebrafish kdm3b (52% identical), Drosophila melanogaster Kdm3 (21% identical). Paralogues in human: KDM3A (37% identical), JMJD1C (36% identical), HR (16% identical).
Diseases named in the same sentence as KDM3B in open-access papers:
KDM3B is named in the same sentence as 47 diseases in open-access papers, as found by Europe PMC text mining. Sharing a sentence is not in itself a finding about the gene and the disease. The quoted sentences say what the papers report.
acute myeloid leukemia (8 papers, 2012 to 2024). Acute myeloid leukemia (AML) is a group of neoplasms arising from precursor cells committed to the myeloid cell-line differentiation. "The four KDM3B pathogenic mutations reported to date have been associated with four different cancers: Wilms tumour and hepatoblastoma in our study, and acute myeloid leukaemia and Hodgkin lymphoma in the study by Diets and colleagues." (PMID 30885698, 2019). "Some studies have shown that KDM3B has potential tumor-suppressive activity in myelodysplastic syndromes, acute myeloid leukemia, acute promyelocytic leukemia, and breast tumors." (PMID 34490047, 2021). "KDM3B may play a tumour-suppressor role in acute myeloid leukemia." (PMID 35886000, 2022). "KDM3B is a H3K9me1/me2-specific demethylase that was initially suspected of inhibiting the tumor activity of hematopoietic malignancies due to its location in the 5q31 chromosome region, which is a frequently deleted region in myelodysplastic syndromes (MDS) and acute myeloid leukemia (AML)." (PMID 31592194, 2019).
leukemia (6 papers, 2018 to 2024). A malignant (clonal) hematologic disorder, involving hematopoietic stem cells and characterized by the presence of primitive or atypical myeloid or lymphoid cells in the bone marrow and the blood. "In line with the flow cytometric results, knocking down KDM3B led to suppressed expression of a leukemia stem cell (LSC) gene signature and a hematopoietic stem cell gene signature." (PMID 31592194, 2019). "By analyzing the expression of the Broad Institute’s CCLE cell lines, we found that KDM3B was significantly highly expressed in human leukemia and lymphoma cell lines compared to other tumor cell lines." (PMID 31592194, 2019). "Future studies using multiomics resource are warranted to investigate the role of KDM3B in other types of leukemia from." (PMID 31592194, 2019). "Such seemingly ambivalent roles of KDM3B may be context-dependent for leukemia, and more studies are required to verify its role in leukemic tumorigenesis." (PMID 38926399, 2024). "Furthermore, analysis of leukemia patient tissues showed that KDM3B levels were increased in ALL-type leukemia patients than in AML-type leukemia patients." (PMID 38926399, 2024). "KDM3B is involved in gene activation in leukemia cells; for review, see." (PMID 37027460, 2023). "However, another study showed that KDM3B was located at the promoter area of the lmo2 gene and drove the occurrence of leukemia." (PMID 34490047, 2021). "In addition, we investigated the potential roles of KDM3B in ATRA mediated leukemia cell differentiation by flow cytometry analysis using CD11b, a granulocytic differentiation marker." (PMID 31592194, 2019). "Tumour-suppressive and tumour-promoting KDM3B activities have been proposed in leukaemia, although somatic driver KDM3B mutations have not been reported." (PMID 30885698, 2019). "Finally, molecular biological techniques and a multi-omics analysis were used to explore the role of KDM3B in differentiation of the leukemia cells after ATRA treatment." (PMID 31592194, 2019). "Taken together, our results showed that KDM3B specifically regulated chromatin accessibility and H3K9me1/me2 modification and taht these regulations are crucial for the NB4 leukemia cell survival and differentiation." (PMID 31592194, 2019). "With the use of a series of experimental assays and using leukemia cell lines (NB4 and PR9), we proved that KDM3B inhibits the survival of APL NB4 cells and it is required for the differentiation of leukemia cells after ATRA treatment." (PMID 31592194, 2019). "Since its discovery and initial characterization, JIB-04 has been used as an inhibitor of the H3K9/K36 demethylase activity of KDM4A in leukemia, the H3K9 demethylase activity of KDM3B in lung cancer, and the H3K4 demethylase activity of members of the KDM5 family in breast cancer and glioblastoma." (PMID 30237855, 2018). "Unlike its level in AML, KDM3B was found to be overexpressed in ALL-type leukemia patients." (PMID 38926399, 2024).
colorectal cancer (5 papers, 2017 to 2025). A primary or metastatic malignant neoplasm that affects the colon or rectum. "In this study, we have identified the induction of KDM3B in the rapamycin-treated or nutrient-deprived colorectal carcinoma cell line, HCT116, caused by starvation media." (PMID 32716961, 2020). "Additionally, KDM3B expression was found vital for the development of the aggressive phenotype in castration‐resistant prostate cancer; it was associated with an increased proportion of cells with a stem cell phenotype, decreased apoptosis, and chemoresistance in colorectal cancer models." (PMID 41046340, 2025). "KDM3B is proposed to be a tumor suppressor gene in myeloid leukemia, colorectal cancer, and breast cancer." (PMID 31822799, 2020). "Here, we report that the level of lysine demethylase 3B (KDM3B) increases in nutrient-deprived HCT116 cells, a colorectal carcinoma cell line, resulting in transcriptional activation of the autophagy-inducing genes." (PMID 32716961, 2020). "Similarly, nuclear co-IP assays in the human colorectal cancer cell line HCT116 verified the interaction between endogenous β-catenin and KDM3A or KDM3B." (PMID 28440295, 2017).
myelodysplastic syndrome (4 papers, 2018 to 2024). A clonal hematopoietic disorder characterized by dysplasia and ineffective hematopoiesis in one or more of the hematopoietic cell lines. "In myelodysplastic syndromes (MDS) and AML, KDM3B is located at the frequently deleted 5q31 chromosome region." (PMID 38926399, 2024).
Wilms tumor (4 papers, 2019 to 2024). An embryonal neoplasm characterized by the presence of epithelial, mesenchymal, and blastema components. "Based on the exome data of possible childhood predisposition genes, two de novo mutations (Asn1141Ser, 916_917delAG) of KDM3B have been found in a child with Wilms tumor." (PMID 38926399, 2024). "This large exome sequencing study suggests that KDM3B variants may be important features of Wilms tumor." (PMID 38926399, 2024). "Analyzing exome sequencing of lymphocyte DNA from Wilms tumor involving 890 individuals has shown that TRIM28, FBXW7, KDM3B, and NYNRIN are new predisposition genes of Wilms tumor." (PMID 38926399, 2024). "The four new Wilms tumour predisposition genes identified—TRIM28, FBXW7, NYNRIN, and KDM3B—are involved in diverse biological processes and, together with the other 17 known Wilms tumour predisposition genes, account for about 10% of Wilms tumour cases." (PMID 30885698, 2019). "KDM3B is one of the genes contributing to a childhood kidney cancer called Wilms tumor." (PMID 38926399, 2024).
acute lymphoblastic leukemia (3 papers, 2024). Leukemia with an acute onset, characterized by the presence of lymphoblasts in the bone marrow and the peripheral blood. "Interestingly, a recent study suggested that the H3K9 demethylase KDM3B represses leukemia cell differentiation, and is upregulated in blood cells of acute lymphoblastic leukemia (ALL) patients." (PMID 39308891, 2024).
Intellectual disability (3 papers, 2019 to 2026). "Recent genetic studies have revealed Kdm3b as a risk gene for cognitive disorders, such as schizophrenia and intellectual disabilities." (PMID 34217333, 2021). "Recent studies have shown that KDM3B mutations are associated with cognitive deficits, including intellectual disability and schizophrenia." (PMID 34217333, 2021). "There are indications that KDM3B and NYNRIN mutations might cause non-malignant phenotypes, particularly intellectual disability." (PMID 30885698, 2019).
lung carcinoma (3 papers, 2018 to 2025).
autism (2 papers, 2019 to 2023). Persistent deficits in social interaction and communication and interaction as well as a markedly restricted repertoire of activity and interest as well as repetitive patterns of behavior. "Over three-quarters of them (n = 3,628, 75.3%) were found in the known genes, including 111 previously unannotated exons in SFARI Autism Genes, such as the exon (chr5:138,380,173–138,380,264) in the KDM3B gene (SFARI gene score = 1)." (PMID 37889749, 2023).
Diets-Jongmans syndrome (2 papers, 2023 to 2026). Diets-Jongmans syndrome (DIJOS) is an autosomal dominant disorder characterized by mild to moderately impaired intellectual development with a recognizable facial gestalt. "A Whole Exome Sequence showed mutations in KDM3B and SIN3A genes, respectively responsible for Diets-Jongmans syndrome (DIJOS) and Witteveen-Kolk syndrome (WITKOS)." (PMID 38314229, 2023).
melanoma (2 papers, 2024 to 2025). A malignant, usually aggressive tumor composed of atypical, neoplastic melanocytes. "On the other hand, KDM3B was found to be crucial in maintaining genome stability in melanoma cells, and KDM3B knockout increased DNA damage, and enhanced cell growth and migration." (PMID 40940894, 2025). "Specifically, we utilized CRISPR/Cas9-mediated genome editing technology to knock out the JMJD1B/KDM3B gene in the B16F10 mouse melanoma cell line." (PMID 39409021, 2024). "To investigate the role of JMJD1B in regulating genome stability and the malignancy of melanoma tumors, we used a JMJD1B/KDM3B knockout in B16F10 mouse melanoma cells to perform tumorigenic and genome instability assays." (PMID 39409021, 2024). "We demonstrate that knocking out the JMJD1B/KDM3B gene in the B16F10 melanoma cell line enhances the tumorigenic properties of the cells both in vitro and in vivo and results in increased genome instability." (PMID 39409021, 2024). "To achieve this, we knocked out the JMJD1B/KDM3B gene in the B16F10 mouse melanoma cell line." (PMID 39409021, 2024).
rhabdomyosarcoma (2 papers, 2024 to 2025). A rare aggressive malignant mesenchymal neoplasm arising from skeletal muscle. "In contrast, the knockdown of KDM3B in PAX3-FOXO1 fusion-positive rhabdomyosarcoma cells reduced the expression of PAX3-FOXO1 target genes by increasing H3K9 methylation within gene promoter regions." (PMID 40940894, 2025). "Suppressed xenograft tumor growth of PAX3-FOXO1 fusion-positive rhabdomyosarcoma and delayed tumor progression were the effects of a dual LSD1 and KDM3B inhibitor, called PFI-90." (PMID 40940894, 2025).
COVID-19 (1 paper, 2025). A disease caused by infection with severe acute respiratory syndrome coronavirus 2. "Our analysis of the cis-eQTL effects of the SNP rs1042665 HSPA9 suggests a complex interplay of gene regulation involving KDM3B, ETF1, FAM53C, KLHL3, and DNAJC18, potentially contributing to COVID-19 severity." (PMID 41009536, 2025).
Ewing sarcoma (1 paper, 2024). A small round cell tumor that lacks morphologic, immunohistochemical, and electron microscopic evidence of neuroectodermal differentiation. "Also, because P3FI-90 exerted potent growth inhibitory activity on Ewing’s sarcoma and osteosarcoma cell lines, KDM3B inhibition could be effective in these pediatric malignancies." (PMID 38402212, 2024).
inflammatory bowel disease (1 paper, 2025). A spectrum of small and large bowel inflammatory diseases of unknown etiology. "Mutations in SETD5 and KDM3B connect OCD with Inflammatory Bowel Disease (IBD), underscoring the polygenic nature and genetic interconnections of these conditions." (PMID 39219434, 2025).
medulloblastoma (1 paper, 2019). A malignant, invasive embryonal neoplasm arising from the cerebellum. "From these analyses, we conclude that mutant DDX3X and loss of GSE1 act as drivers of SHH medulloblastoma tumorigenesis, while mutations in KDM3B may represent a passenger." (PMID 31204176, 2019). "Expression of GSE1 and KDM3B correlates inversely with survival in patients with medulloblastoma." (PMID 31204176, 2019).
myeloid malignancies (1 paper, 2021). "In myeloid malignancies, KDM3A has been shown to demethylate H3K9me2, while KDM3B is associated with histone demethylase activity towards H3K9me1–2." (PMID 34944554, 2021).
tumor (20 papers, 2017 to 2026). "Contrary to the implicated tumor-suppressive role of KDM3B in BCa, another study has identified a possible oncogenic role of KDM3B in BCa progression." (PMID 38926399, 2024). "Strikingly, both KDM3B depletion and treatment with the KDM3B-selective inhibitor P3FI-90 significantly suppresses tumor progression and mitigates resistance to immune checkpoint blockade (ICB) therapy." (PMID 42201640, 2026). "Oncomine database shows that KDM3B is upregulated in normal breast tissues compared to BCa tissues, suggesting its role as a tumor suppressor." (PMID 38926399, 2024). "Despite the tumor suppressive role associated with PRL-3, KDM3B has also been reported to contribute to CRC recurrence and chemoresistance via activating the Wnt signaling pathway." (PMID 38926399, 2024). "In line with this, KDM3B overexpression repressed colony formation of AML cells, implicating the tumor-suppressive role of KDM3B in AML." (PMID 38926399, 2024). "Here, we identify and elucidate a novel differentiation-suppressive model of APL involving the histone demethylase KDM3B, which has been identified as a suppressor of the tumor genes involved in hematopoietic malignancies." (PMID 31592194, 2019). "For instance, it has been shown that the KDM3B gene exhibits potential tumor-suppressive activity in AML and it transcriptionally regulates HOXA1 via retinoic acid response elements." (PMID 31426381, 2019). "Among the differential ASEs, we noted the loss of predicted nuclear localization signals (NLS) for KDM3B (Lysine-specific demethylase 3B), a histone demethylase with potential tumor suppressor activity." (PMID 28493890, 2017). "KDM3B was first reported as a tumor-suppressor gene against hematopoietic malignancies." (PMID 38926399, 2024). "Also, expression of KDM3B is inversely correlated with lymph node status, Dukes’ classification, and tumor staging." (PMID 38926399, 2024). "In all, KDM3B is reported to carry tumor-suppressive in AML, yet oncogenic properties in ALL." (PMID 38926399, 2024). "KDM3B has been proposed to act as a tumor suppressor in myeloid disorders." (PMID 34944554, 2021). "First, the expression of KDM3B across tumor types were tested." (PMID 31592194, 2019). "Consequently, KDM3B inhibitors suppress tumor growth by inhibiting demethylase activity." (PMID 41007433, 2025). "Genetic or pharmacologic inhibition of KDM3B facilitates the recruitment and activation of CD8+ T cells, thereby suppressing tumor growth in TNBC mouse models." (PMID 42201640, 2026). "PGG dose-dependently inhibited the ANP32E/KDM3B/EGFR axis in vitro and suppressed tumor growth in vivo." (PMID 41980942, 2026). "KDM3B and KDM3C can function as oncogenes or tumor suppressors depending on different cancers types or other cellular conditions." (PMID 38926399, 2024). "Various protein-protein interactions and cross-talks between different pathways decide the fate of KDM3B and KDM3C proteins to function as oncogenes or tumor suppressors." (PMID 38926399, 2024). "In parallel, an overall increase in H3K9me2 erasers (KDM3B and KDM4A in basalioma, and KDM3A in the other two tumor types) and a bladder-specific decrease in the reader PRDM6 involved in K9 dimethylation were found." (PMID 37569534, 2023). "Compared to other tumor type’s patients, AML patients had the highest expression of KDM3B." (PMID 31592194, 2019).